FOXA2 (forkhead box A2)
Diseases named in the same sentence as FOXA2 in open-access papers (continued):
Sharing a sentence is not in itself a finding about the gene and the disease.
tumor (continued). "FOXA1 and FOXA2 play different biological functions in tumor development by regulating the expression of multiple genes, which are closely related to cancer development and chemoresistance." (PMID 38605023, 2024). "Organoid lines also exhibited somatic mutations in RCC‐related genes which were in concordant with respective tumor including ESPL1, SMARCB1, RAB21, NCOR1, NLRC5, NOTCH2, and FOXA2 mutations." (PMID 38923304, 2024). "Examining TF regulatory networks, FOXA1 and FOXA2 promoter and enhancer regions were hypomethylated when compared to non-tumor control tissue." (PMID 38173042, 2024). "FOXA2 is expressed at lower levels in HCC tissues than in paracancerous tissues, and low levels of FOXA2 expression correlate with tumor aggressiveness." (PMID 38605023, 2024). "For example, miR-200a inhibited the expression of FOXA2 and reduced tumor metastasis and growth in HCC." (PMID 39199296, 2024). "Correspondingly, tumor volume and weight in FOXA2 knockdown mice were significantly reduced compared to those in control mice." (PMID 38072043, 2023). "The forkhead box transcription factor A2 (FOXA2) is a transcription factor and plays a key role in embryonic development, metabolism homeostasis and tumor cell proliferation; however, its regulatory potential in CRC is not fully understood." (PMID 37875418, 2023). "FOXA2 deletion contributed to tumor suppression and chemoresistance in CRC by inducing ferroptosis via the Nrf2/GPX4 signaling suppression." (PMID 37875418, 2023). "IHC staining validated the much lower expression of KI‐67, Fibronectin, GPX4, and Nrf2 in tumor samples from the OXA/sh‐FOXA2 group of mice, which was comparable with the OXA and sh‐FOXA2 single treatment groups." (PMID 37875418, 2023). "Western blot analysis and quantitative RT‒PCR confirmed that the expression levels of FOXA2 in fresh tumor tissues from 67 patients were significantly higher than those in matched adjacent normal tissues." (PMID 38072043, 2023). "Here, it is found that FOXA2 expression is markedly up‐regulated in tumor samples of CRC patients as compared with the normal tissues, which is closely associated with the worse survival in patients with CRC." (PMID 37875418, 2023). "As expected, sh‐FOXA2 effectively reduced the tumor size and growth rates compared with the sh‐NC group, but promoting FOXA2 expression significantly facilitated the tumor growth in mice, accompanied with much higher tumor weights." (PMID 37875418, 2023). "Subcutaneous tumor growth of ACHN cells with the FOXA2-K264R mutant or wild-type FOXA2 was monitored." (PMID 38072043, 2023). "FOXA2 is connected to more aggressive tumor behavior because it plays a part in the mechanisms of proliferation." (PMID 37626655, 2023). "Correspondingly, tumor volume and weight in FOXA2-K264R mutant mice were significantly increased compared to those in wild-type FOXA2 mice." (PMID 38072043, 2023). "Subcutaneous tumor growth of A498 cells with FOXA2 shRNA-mediated stable knockdown or scrambled control was monitored." (PMID 38072043, 2023). "Tumor cells with FOXA2 knockdown grew significantly slower than those with the scramble control in the same mouse." (PMID 38072043, 2023). "Tumor cells with the FOXA2-K264R mutant grew significantly faster than those with wild-type FOXA2 in the same mouse." (PMID 38072043, 2023). "Foxa2/Pten mouse model establishes in vivo tumor suppressor functions of Foxa2 and potent synergism with Pten." (PMID 35703180, 2022). "Taken together, these results demonstrated that Foxa2 was a potent tumor suppressor where functional inactivation cooperated with Pten loss." (PMID 35703180, 2022). "Sixth, diverse analyses of cell lines and organoids derived from the mouse Foxa2/Pten primary ECs further supported a tumor suppressor role for Foxa2 via the suppression of EMT-associated invasive and metastatic phenotypes." (PMID 35703180, 2022).
tumor (continued). "Functional studies using Foxa2/Pten primary tumor–derived organoids and cell lines show the roles of Foxa2 in suppressing cell growth and EMT phenotypes." (PMID 35703180, 2022). "Several studies have confirmed the role of FOXA2 as a tumor suppressor gene or oncogene in different cancers by activating or downregulating different pathways and proteins." (PMID 36289750, 2022). "Quantitative RT-PCR (RT-qPCR) revealed that genes representing mesodermal (T, Kdr), endodermal (Foxa2, Gata4/6, Sox17) and ectodermal (Fgf5, Sox11 for primitive ectoderm) differentiation were generally activated in tumor." (PMID 33468253, 2021). "Intriguingly, after castration in mice bearing the LTL‐331 tumor line, FOXA2 expression was followed by the upregulation of LINC00261, peaking at about 12wks, as the tumor cells transdifferentiate into the neuroendocrine LTL‐331R tumor line." (PMID 33793068, 2021). "The highly expressed miR-765 targets Forkhead box A2 (Foxa2), resulting in a decrease in Foxa2 expression, and enhancement of tumor stem cells renewal, and apoptosis inhibition." (PMID 33267910, 2020). "Our findings demonstrate that FOXA2 downregulates SLC25A13 expression and function, in agreement with the reported role of FOXA2 as tumour suppressor in HCC." (PMID 30995827, 2019). "The survival analysis showed that the tumor-free survival rates at 1 year and 3 years in the high FOXA2 expression group were 68.6% and 32.9%, respectively, and were 34.0% and 9.9%, respectively in the low FOXA2 expression group (p < 0.001)." (PMID 31689237, 2019). "Subsequently, mouse subcutaneous xenograft experiments were performed to detect the effects of PGC-1β and FOXA2 on tumor growth in vivo." (PMID 31007610, 2019). "PGC-1β cooperating with FOXA2 can regulate the tumor cells proliferation, migration and apoptosis in vitro and vivo." (PMID 31007610, 2019). "To analyze the effect of a SOX2-/FOXA2-deficiency on TCam-2 cells in vivo, we xenografted TCam-2-ΔSOX2 and TCam-2-ΔSOX2/FOXA2 cells into the flank of nude mice and analyzed the tumor tissues after six and twelve weeks." (PMID 31130628, 2019). "FOXA2 is a member of forkhead/winged-helix family, which plays crucial role in organ genesis, cellular metabolism, and tumor development." (PMID 31007610, 2019). "Compared with adjacent tumor tissue, the expression of FoxA2 was decreased in ICC tissues according to the Western blot analysis." (PMID 31689237, 2019). "FOXA2's dual role in cancer development as a tumor suppressor and a tumor promoter in various cancers has been reported by several studies." (PMID 31781476, 2019). "A dramatic increase in both cell invasion and migration capacity was observed, supporting a tumour suppressor function for FOXA2-DS-S transcripts similar to the reported role of FOXA2 in cancer cells." (PMID 29540241, 2018). "We found that concomitant deletion of both Foxa1 and Foxa2 led to an approximately 10-fold reduction in tumor burden when measured at 5 weeks post-initiation." (PMID 30475207, 2018). "We analysed GATA6, E-cadherin and FOXA2 by IHC in tumours (n=25) using 4 mm core tissue microarrays (TMA), allowing for detection of intratumour heterogeneity." (PMID 27325420, 2017). "For example, FOXA1 and FOXA2 cooperate with nuclear hormone receptors in endocrine-driven tumors of the breast, prostate and liver." (PMID 29155818, 2017). "Next, we focused on the identification of genes under the control of FoxA1 and FoxA2 with the capacity to support tumour growth in xenograft tumours from implanted MCF7 and MDA231 cells, with a specific focus on metabolic functions." (PMID 27045898, 2016). "In MTC, based on the present findings, it is conceivable that infiltrating tumor cells with diminished Foxa2 and E-cadherin expression are more prone to metastasize than clusters of Foxa2+ cells that are constrained by E-cadherin-based adhesion." (PMID 26395490, 2015).
tumor (continued). "By contrast, although most cells showed nuclear staining of Foxa2 the expression level was weaker or occasionally lost towards the tumor periphery facing the stromal compartment." (PMID 26395490, 2015). "We investigated this possibility by monitoring Foxa2 in infiltrating tumor cells that displayed signs of EMT." (PMID 26395490, 2015). "The data further underpin distinct functions of Foxa1 and Foxa2 in both embryonic and tumor development." (PMID 26395490, 2015). "This showed generally strong immunoreactivity for Foxa1 and Foxa2 in both primary tumor nodules and lymph node metastases." (PMID 26395490, 2015). "In another study, the K-RasG12V-induced tumor model intercrossed with MAPK14Δ/Δ mice (MAPK14 deletion in adult) demonstrated high tumor frequency with low expression of C/EBPα and FoxA2 in the lung." (PMID 23437297, 2013). "In tumor T9, active β-Catenin protein was down-regulated but FoxA2 protein was up-regulated as compared with its paired normal control N9." (PMID 24244486, 2013). "The ovarian metastases demonstrated upregulation of FOXA2 by immunohistochemistry relative to the subcutaneous tumor generated from the parental line, implying that subclones expressing FOXA2 might be selectively contributing to metastasis." (PMID 40419484, 2025). "Specifically, we found that tumor cells with brain metastasis tendency could inhibit ABAT by inhibiting FOXA2 expression, thereby reducing the breakdown of GABA and increasing the accumulation of GABA." (PMID 39972344, 2025). "The regulators in C1 LYZ+ tumor cells were mainly FOXA2, PDX1, GATA6, and PPARG." (PMID 40230840, 2025). "Moreover, a long non-coding RNA, FTX is shown to sponge miR-200a thereby impairing the inactivation of miR-200a target, FOXA2, a transcription factor, acting as a tumor suppressor that attenuates tumor cell proliferation, migration, and invasion." (PMID 41271627, 2025). "FOXA1 and FOXA2 regulate the hypoxic transcriptional program inversely when PCa is in a hypoxic tumor microenvironment, and which of FOXA1 and FOXA2 tends to regulate HIF1A may depend on the high or low expression of FOXA1 and FOXA2 in the PCa phenotype." (PMID 38605023, 2024). "Notably, the different regulatory functions of FOXA1 and FOXA2 in tumorigenesis are also substantially different in different sexes and various subtypes of cancer, which can act as oncogenes or tumor suppressors." (PMID 38605023, 2024). "Furthermore, KI‐67, a marker of tumor cell proliferation, and Fibronectin were also found to be highly down‐regulated by FOXA2 ablation, while being promoted in tumor tissues with FOXA2 over‐expression." (PMID 37875418, 2023). "HDAC3 initiates tumor activity by regulating the FOXA2-mediated FTO/m6A/MYC axis." (PMID 37932821, 2023). "Recent studies have demonstrated that FOXA2 could cooperate with KrasG12D activation during tumor development." (PMID 38071219, 2023). "Additionally, injection of stable FOXA2 knockdown or over‐expression CRC cells into BALB/c nude mice further supported the effects of FOXA2 on tumor growth in vivo." (PMID 37875418, 2023). "Additionally, stronger FOXA2 was detected in tumor samples collected from oe‐FOXA2 mice than that of the oe‐NC group, which was confirmed by IHC staining." (PMID 37875418, 2023). "In addition, we found that the expression level of FOXA2 in RCC positively correlated with the tumor stage and differentiation state of the cancer cells, although differences in lymph node metastasis and distant metastasis were not significant." (PMID 38072043, 2023). "Western blot results showed evidently reduced FOXA2 expression in tumor tissues from sh‐FOXA2 mice." (PMID 37875418, 2023). "Our results provide compelling evidence that FOXA2 is a tumor suppressor in EC." (PMID 35703180, 2022). "FOXA2 has been reported as a tumor suppressor in different cancers." (PMID 36289750, 2022).
tumor (continued). "Transcriptome and cistrome analyses revealed that FOXA2 broadly controls gene expression programs through modification of enhancer activity in addition to regulating specific target genes, rationalizing its tumor suppressor functions." (PMID 35703180, 2022). "This mouse model thus provides formal genetic proof that Foxa2 functions as a tumor suppressor." (PMID 35703180, 2022). "Similarly, FOXA2 has been reported to be a tumor suppressor gene in various cancers and is a target of oncogenes, such as in pancreatic cancer, liver cancer, oral cancer, and cervical cancer." (PMID 36289750, 2022). "Moreover, the expression of GNG8, MYO1H, and TNFRSF13B was significantly down-regulated, while the expression of SYT14 and FOXA2 was significantly up-regulated in the samples with higher tumor stage." (PMID 34322156, 2021). "e. if FOXA2 is detectable in a patient's tumour sample, early more aggressive treatment may be recommended before YST outgrowth renders these progressive treatment‐resistant GCTs incurable." (PMID 33448076, 2021). "Moreover, genes representing mesodermal or/and endodermal tissue differentiation (ACP5, ACTA2, BGLAP, CTSK, DESMIN, FOXA2) were activated in tumor." (PMID 33468253, 2021). "FOXA2 itself is suggested to be important for pancreas development and potential tumor suppression; however, controversy exists as to whether FOXA2 could also act as an oncogene in some cancer types." (PMID 32414223, 2020). "We knocked down FoxA2 expression by siRNA and demonstrated that the decrease in FoxA2 expression in ICC cells could similarly promote tumor cell proliferation and invasion." (PMID 31689237, 2019). "The decrease in FOXA2 expression could widely influence tumor-related signaling pathways, and can thus influence tumor prognosis." (PMID 31689237, 2019). "Also, we found the combination of PGC-1β interference with FOXA2 overexpression significantly inhibited cell proliferation and migration in vitro as well as tumor growth in vivo." (PMID 31007610, 2019). "Notably reduced expression of AT2 markers begins early in tumor development and occurs despite sustained NKX2-1, FOXA1, and FOXA2 expression in tumor cells." (PMID 31452510, 2019). "There are some parallels between tumor progression and early stages of endoderm differentiation, where LINC00261/DEANR1 acts in cis by recruiting the EMT-associated transcription factors SMAD2/3 to the FOXA2 promoter." (PMID 30597925, 2018). "Indeed, by in vivo studies on mice that received transplanted tumors harboring Numb knockdown Hep3B cells infected with retrovirus expressing FOXA2 continued to show tumor growth even in the presence of FOXA2." (PMID 30154786, 2018). "For example, FOXA2 and its tapRNA FOXA2-DS-S were found significantly down-regulated in lung tumour compared to normal samples (p values = 3 × 10−16 and 2 × 10−22, respectively), effectively separating tumour samples from controls." (PMID 29540241, 2018). "Interestingly, we observed a positive correlation between the expression of LINC00261 and its neighboring gene FOXA2 in normal as well as lung tumor samples, with both genes being suppressed during tumor progression as well as TGFβ-induced EMT." (PMID 30597925, 2018). "In this sense it will be also very interesting to explore the expression of CTR in primary and metastatic MTC lesions, as well as in the invasive front vs tumor bulk, in combination with lineage specific markers (Foxa1/Foxa2) and epithelial–mesenchymal transition markers." (PMID 28929017, 2017). "Loss of Foxa2, as observed in MTC cells in close contact with the tumor stroma, suggested that a similar mechanism might facilitate tumor spreading in vivo." (PMID 26395490, 2015). "Cytoplasmic colocalization of Foxa2 and E-cadherin might reflect neosynthesis as new tumor cell clusters form." (PMID 26395490, 2015).
tumor (continued). "In contrast to embryonic precursor cells, C cell-derived tumor cells invading the stromal compartment downregulated Foxa2, foregoing epithelial-to-mesenchymal transition designated by loss of E-cadherin; both Foxa2 and E-cadherin were re-expressed at metastatic sites." (PMID 26395490, 2015). "Moreover, single tumor cells with only patchy remnants of E-cadherin were Foxa2– (C′′) or showed strong E-cadherin staining that colocalized with Foxa2 in the cytoplasm (C′′′)." (PMID 26395490, 2015). "The twelfth TF (FOXA2) was deregulated in the MSS tumours only." (PMID 19156145, 2009). "Therefore, the subcellular localization of FOXA2 may influence its oncogenic or tumor-suppressive effects." (PMID 36289750, 2022). "Compared with NE-4C cells, the tumor showed a general tendency of upregulation of a series of genes representing neural stemness, genes representing neuronal differentiation, and genes representing mesodermal (Acta2, T, Desmin, Kdr) and endodermal tissue (Afp, Foxa2) differentiation." (PMID 33468253, 2021). "Therefore, low FOXA2 expression in ICC may indicate a higher tumor stage and dismal clinical outcome." (PMID 31689237, 2019). "Notably, the expression levels of FoxA2 were inversely correlated with tumor grade." (PMID 31689237, 2019). "However, whether tumor progression in vivo involves a similar mechanism governed by downregulation of Foxa2 was previously unknown." (PMID 26395490, 2015). "Notably, FoxA2 inhibition is less effective in attenuating NE tumor formation." (PMID 21037926, 2010). "Supporting the primary tumor analysis, we found that the FOXA2 locus was open in all 3 ASCL1+/FOXA2+ PDX tumors, but closed in the ASCL1+/FOXA2– PDX tumor." (PMID 40419484, 2025). "Despite a clear inhibitory effect of FOXA2 suppression on the metastatic activity of SCLC cells in mice, this had no apparent effect on SCLC viability, proliferation in vitro, or subcutaneous tumor growth in vivo." (PMID 40419484, 2025). "In immunohistochemical staining, all YST‐like tumor tissues were focally positive for the YST markers SOX17 and FOXA2 and showed a YST‐like morphology in hematoxylin and eosin staining." (PMID 40025812, 2025). "We demonstrated that the upregulation of INHBA initiated by FOXA2 promoted MITF-mediated EMT and tumor progression in response to sustained MMA stimulation." (PMID 38252148, 2024). "When PCa is in a hypoxic tumor microenvironment, both FOXA1 and FOXA2 regulate the hypoxic transcriptional program by binding to HIF1A." (PMID 38605023, 2024). "In contrast, luminal A/B tumor cells and LM cells showed high accessibility for the ER ESR1, as well as forkhead proteins, including FOXA2 and FOXP1, GATA3 and other GATA-box TFs, and HNF1A." (PMID 39478117, 2024). "IHC staining confirmed the promotive effects of FOXA2 on GPX4 and Nrf2, as indicated by the obviously enhanced positive expression of GPX4 and Nrf2 in tumor samples collected from oe‐FOXA2 mice." (PMID 37875418, 2023). "PPI network analysis revealed these genes and modules were mainly related to tumor progression (LOXL1, IKBKE, LNX1, FOXA2, FGF17, and FGF2) and immune response (STAT4, IL23R, LTA, ITK, and IL19)." (PMID 36611170, 2023). "We similarly found that FOXA2 knockdown markedly reduced the proliferative, migratory, and invasive properties of CRC cells in vitro and efficiently restrained tumor growth in vivo by using various CRC mouse models." (PMID 37875418, 2023). "Double IF staining finally suggested that mice with FOXA2 absence exerted lower GPX4 and Nrf2 positive expression in tumor areas of AOM/DSS‐treated colons." (PMID 37875418, 2023). "Among these genes, SPINT2, LNX1, FOXA2, and SOSTDC1 were reported to be related to tumor progression, whereas TYROBP, TREM2, IL23R, CSF2RB, TRAF1, and TGFBR1 were closely associated with immune response." (PMID 36611170, 2023).